PDGFRB (platelet derived growth factor receptor beta)
Diseases named in the same sentence as PDGFRB in open-access papers (continued):
Sharing a sentence is not in itself a finding about the gene and the disease.
pancreatic cancer (44 papers, 2010 to 2026). "In this study, 47Sc was used to label the affibody targeting PDGFRβ to explore its distribution characteristics in pancreatic cancer and the therapeutic effect of radionuclides." (PMID 41491696, 2026). "Platelet-derived growth factor receptor β (PDGFRβ) overexpressed on pericytes was suggested as a target molecule for RGR in a pancreatic cancer mouse model." (PMID 35635308, 2022). "Hence, given the reported expression of PDGFRβ and c-Kit in pancreatic cancer, the implication of mast cells in pancreatic cancer development, and association of FAK with chemoresistance, it is hypothesised that masitinib may be of therapeutic potential in this disease." (PMID 20209107, 2010). "Finally, PDGFRB-targeted diagnostic and therapeutic approaches are likely to be valuable in additional tumour types such gastrointestinal stromal tumours (GIST) and stroma-rich carcinomas such as pancreatic cancer." (PMID 36139509, 2022). "COL1A1, COL1A2, ACTA2, PDGFRB and FAP displayed a significant positive correlation with this gene dataset in melanoma tumours (SKCM), whereas in pancreatic tumours (PAAD), that correlation was even stronger owing to their highly desmoplastic TME." (PMID 35654839, 2022).
leukemia (42 papers, 2008 to 2025). A malignant (clonal) hematologic disorder, involving hematopoietic stem cells and characterized by the presence of primitive or atypical myeloid or lymphoid cells in the bone marrow and the blood. "Intriguingly, overexpression of PDGFRβ is typically associated with worse prognosis in leukemia and myeloma patients." (PMID 34884535, 2021). "Histological examination revealed extensive infiltration of TERF2::PDGFRB‐positive leukaemia cells into various tissues, including bone, liver and spleen." (PMID 38323741, 2024). "RNA sequencing (RNA-seq) of leukemia cells revealed the presence of a novel NRIP1::PDGFRB fusion gene, where an untranslated region of NRIP1 intron 3 was connected to exons 12–23 of PDGFRB." (PMID 38071343, 2023). "On the other hand, there are five different translocation described for PDGFRB in leukemia cells, which lead to constitutively active receptor production." (PMID 24709958, 2014). "The TERF2::PDGFRB gene fusion resulted in fully penetrant leukaemia development." (PMID 38323741, 2024). "Moreover, our experiments using BALB/c mice have shown that Ba/F3 cells carrying the TERF2::PDGFRB fusion gene are capable of inducing leukaemia in vivo and are notably sensitive to imatinib treatment." (PMID 38323741, 2024). "Furthermore, targeted RNA sequencing (RNA‐seq) of leukaemia blast cells revealed the presence of a novel TERF2::PDGFRB fusion gene, involving an in‐frame fusion of exon 9–23 of PDGFRB with exon 1–8 of the TERF2 gene." (PMID 38323741, 2024). "Similarly, TPM3 accelerated leukemia via fusion with PDGFRB." (PMID 36639822, 2023). "We exposed four leukemia and four NB cells to multi-kinase (KIT, PDGFRa, and PDGFRb) inhibitor-imatinib in the presence of belinostat or hydrazostat." (PMID 34944663, 2021). "CCDC6 has been involved in different rearrangements with several tyrosine kinases (RET, PDGFRb, ROS1, FGFR2) in several tumours (thyroid, lung, leukemia, breast, iCCA)." (PMID 29455670, 2018). "Although FAP and PDGFRβ expression was strongly diminished in LYNKO BMSC and both molecules were associated with the leukemia protective function of stromal cells, both FAP- and PDGFRβ-knockdown did not impair stromal feeding capacity in CLL co-culture." (PMID 36899005, 2023). "In leukemia, CCDC6 rearranged with PDGFRβ contributes an aminoterminus portion of 368 aminoacids." (PMID 29455670, 2018). "This inhibitor was tested to be exclusively specific for PDGFRβ in leukemia and vascular smooth muscle cells, not targeting PDGFRα and c-KIT." (PMID 23900414, 2013).
lung cancer (42 papers, 2010 to 2026). A malignant neoplasm involving the lung. "We found eight genes relevant to lung cancer (PDGFRB, RET, KRAS, KEAP1, ROS1, STK11, MET and ALK), for which integrating clinical data with our TME features clearly improves the ability to predict mutations in these genes." (PMID 36131239, 2022). "M5 expressed pericyte-associated genes (RGS5, PDGFRB, NES, THY1, KCNJ8) and showed strong similarity to curated pericyte signatures, including pan-cancer C8_RGS5 pericytes, healthy human prostate pericytes and pericytes from lung cancer." (PMID 41378308, 2025). "Interactions with the bone stroma appear to drive lung cancer homing and colonization, whereby factors expressed by bone marrow stromal cells, osteoblasts, and osteoclasts, such as platelet derived growth factor receptor beta, promote metastatic lung cancer engraftment in bone." (PMID 31330786, 2019). "Among all the tested genes, the top-performing ones were NUMA1 and JAK1 in KIRC, PDGFRB and BCL6 in lung cancer, IRS2 in endometrial cancer, and GNAS in BRCA, each with an AUC of at least 0.89." (PMID 38491101, 2024). "Further in lung cancer groups, scRNA analysis showed higher expressing levels of COL1A1M COL1A2, PDGFRA and PDGFRB in identifying the CAF clusters specifically." (PMID 39034310, 2024). "In vivo generated afatinib-resistant clones of H1975 lung cancer cells showed decreased expression of EGFR, HER2, HER3 and HER4 and increased expression of MET, c-KIT and PDGFRβ." (PMID 31557260, 2019). "PCDF cells stained positive for the fibroblast markers PDGFRβ, which was in contrast to human PCa PC346C cells, and human lung cancer SW1573 cells." (PMID 29808619, 2018). "The miR-34 family is down-regulated in lung cancer, leading to the up-regulation of miR-34 target genes, such as MET, BCL2, PDGFR-α (PDGFRA), and PDGFR-β (PDGFRB)." (PMID 27005669, 2016). "Interestingly, Girdin depletion increased PDGβ-induced degradation of PDGFRβ and thus inhibited PDGF signaling and PKM2 phosphorylation in lung cancer cells." (PMID 36428781, 2022). "We found PDGFRB is highly expressed in the non‐responding group of mesenchymal‐like cells, previous studies have shown PDGFR family play a significant role in brain, breast, colorectal, melanoma and lung cancers, suggesting that it may be potential marker for treatment response." (PMID 40420636, 2026). "The markers of COL1A1, COL1A2, and FAP are significantly highly expressed in lung cancer, compared to normal tissues, while PDGFRA, PDGFRB, and ACTA2 either failed to be differentially expressed in cancer tissues, or were expressed in relative lower levels." (PMID 39034310, 2024).
renal cell carcinoma (42 papers, 2008 to 2025). "Of the potential pathways revealed by kinomic profiling, PDGFRβ was chosen for further investigation as its expression is associated with metastasis and poor prognosis in other solid tumors including renal cell carcinoma." (PMID 31565187, 2019). "In renal cell carcinoma, histone lactylation levels are elevated, which facilitates the transcription of platelet-derived growth factor receptor β (PDGFRβ) and stimulates the proliferation of renal cell carcinoma." (PMID 39683818, 2024). "We chose to examine PDGFRβ because inhibition of PDGFRβ signaling inhibited tumor growth and degree of lung metastasis in an in vivo murine model of renal cell carcinoma." (PMID 31565187, 2019). "Additionally, PDGFRβ expression has been shown to correlate with poor prognosis in renal cell carcinoma." (PMID 31565187, 2019). "Axitinib is an inhibitor of VEGFR1, VEGFR2, VEGFR3, PDGFRα, and PDGFRβ, approved by the U.S. FDA in 2012 for the second-line therapy for advanced renal cell carcinoma (RCC)." (PMID 37377855, 2023). "Pazopanib, a PDGFRα and PDGFRβ/ VEGFR/ c-kit-targeting tyrosine kinase inhibitor, has been approved by Food and Drug Administration (FDA) for soft tissue sarcoma and renal cell carcinoma." (PMID 28511645, 2017). "In renal cell carcinoma, the inactivation of Von Hippel-Lindau (VHL) promotes the H3K18la modification of platelet-derived growth factor receptor β (PDGFRβ), activating its transcription and driving tumor progression by H3K18la-PDGFRβ positive feedback loop." (PMID 40589733, 2025). "Studies have shown that high expression of PDGFRβ is predictive of poorer prognosis in renal cell carcinoma but no studies have examined its expression in WT." (PMID 31565187, 2019).
colorectal cancer (39 papers, 2008 to 2025). A primary or metastatic malignant neoplasm that affects the colon or rectum. "Elevated levels of PDGFRβ were associated with an increased risk of recurrence in breast and colorectal cancers." (PMID 39780187, 2025). "In colorectal cancer, lower PDGFRβ expression was associated with better prognosis and PDGFRβ knockdown using siRNA resulted in decreased colorectal cancer proliferation, growth, and invasion." (PMID 34206917, 2021). "Platelet-derived growth factor receptor β (PDGFRβ), which is a receptor tyrosine kinase and is also a downstream signal of TGFβ, is associated with invasion and metastasis in colorectal cancer." (PMID 32899998, 2020). "In particular, the G-allele genotype of PDGFRβ exon 19 SNP (rs246395), encountered in 58% of tumor samples from colorectal cancer patients, was associated with increased pathway activation and significantly poorer survival." (PMID 23146028, 2012). "This study has identified, for the first time, PDGFRβ genetic variants with relevant clinical and biological implications in colorectal cancer." (PMID 23146028, 2012). "Recently, we have also reported that SNPs in the PDGFRβ gene are related to increased levels of receptor and signaling, promoting chemotherapy resistance in colorectal cancer patients." (PMID 24758355, 2014). "In addition, the CC genotype was correlated with increased PDGFRB protein levels and pathway activation in colorectal cancer cell lines." (PMID 35406617, 2022). "Moreover, bioinformatics screening of colorectal cancer patients demonstrated that expression of PDGFRβ is strongly correlated with that of TGFβ signaling-related genes." (PMID 30344924, 2018). "Indeed, the PDGF/PDGFRβ interaction is known to play a key role in the promotion of several malignancies including colorectal carcinoma." (PMID 22205974, 2011). "PDGFRβ+ CAFs, when stimulated by PDGF, can enhance migration and invasion of co-cultured colorectal cancer cells in a stanniocalcin-1-dependent manner." (PMID 39780187, 2025). "To functionally validate the regulatory relationship between CST4 and PDGFRB suggested by bioinformatic analyses, we performed in vitro knockdown experiments in HCT116 colorectal cancer cells." (PMID 41040534, 2025). "In this study, using cell assay techniques, transcript and protein analyses in colon cancer patient tissue, and the cell line, we show that PDGFRβ stimulation by TGFβ and PDGF-D increases the THBS4 secretion via IP3R and STIM1 in colorectal cancer." (PMID 32899998, 2020). "We identified that PDGFRβ and THBS4 are overexpressed in tumor tissues of colorectal cancer patients, and that PDGF-D expression increased after TGFβ treatment in the colon cancer cell line DLD-1." (PMID 32899998, 2020). "Supporting this, PDGFRβ blocking agent (CDP-860) had been shown to cause ascites and/or PE in patients with advanced ovarian and colorectal cancer, which was not a disease-specific phenomenon." (PMID 38558869, 2024). "In colorectal cancer, THBS4 is critical in PDGFRβ-mediated tumor progression." (PMID 34804159, 2021). "Thus, the study of multiple regions of CMS4 colorectal cancers and the analysis of PDGFRA, PDGFRB, PDGFC and KIT showed the existence of a consistent intratumor heterogeneity." (PMID 29652830, 2018). "Both a DNA vaccine against PDGFRβ as well as PDGFR inhibition by imatinib alone or in combination with irinotecan, suppressed growth and dissemination of human colorectal cancer cells injected into mice, suggesting that increased PDGF signalling to stromal cells is a determinant for malignancy." (PMID 18506144, 2008).
gastric cancer (36 papers, 2010 to 2025). A primary or metastatic malignant neoplasm involving the stomach. "Overexpression of PDGFRβ has been associated with PTX resistance in gastric cancer." (PMID 40282535, 2025). "PDGFRB that encodes platelet-derived growth factor receptor-β is overexpressed in gastric cancer tissue and associated with poor 5-years overall survival in patients with stage II/III gastric cancer receiving adjuvant chemotherapy with S-1, serving as an independent predictor of survival." (PMID 34900998, 2021). "That is, high expression of PDGFRB can harm the prognosis of gastric cancer by promoting tumor angiogenesis and regulating the tumor immune microenvironment." (PMID 40128057, 2025). "High expression of PDGFRB has also been shown to negatively affect the prognosis of gastric cancer patients by promoting angiogenesis and modulating the tumor immune microenvironment." (PMID 39484208, 2024). "The relative expression of PDGFRα and PDGFRβ in gastric cancer cells increased with increasing LOX concentration but decreased with increasing BAPN concentration." (PMID 38434983, 2024). "The expression of platelet-derived growth factor receptor (PDGFR)α and PDGFRβ in gastric cancer cells was detected by Western blot." (PMID 38434983, 2024). "The relative expression of PDGFRα and PDGFRβ in gastric cancer cells was up-regulated with increasing LOX and downregulated with increasing BAPN (P < 0.05)." (PMID 38434983, 2024). "Hub genes of COL1A1, COL4A1, COL12A1, and PDGFRB were overlapped in both PPI hub gene list and the turquoise module with significant association with the prognosis in gastric cancer." (PMID 35111208, 2021). "NRP1 is a prognostic marker, hypomethylated and co-expressed with PDGFRB resulting in reduced gastric cancer survival." (PMID 33521362, 2021). "Consistent with its tumor suppressor potential, ectopic expression of latexin induced differential expression of several tumor related genes, including Maspin, WFDC1, SLPI, S100P, and PDGFRB, in gastric cancer cells." (PMID 21466706, 2011). "Besides that, Gli2 induces transcription of PDGFRB and promotes cancer stem cell properties in gastric cancer." (PMID 32493490, 2020). "Notably, gastric cancer patients with higher expression of PDGFRB had poor prognosis in TCGA." (PMID 35664061, 2022). "With inhibition of PDGFRα and PDGFRβ using AG1295 or AG1296, VM formation in gastric cancer cells decreased (P <0.05), but the number of VM structures increased while LOX was added (P < 0.05)." (PMID 38434983, 2024). "PDGFRB has been shown to be a prognostic biomarker for gastric cancer, but there is no holistic pan-cancer study on PDGFRB." (PMID 40128057, 2025). "However, in recent gastric cancer research, studies have demonstrated that targeting both PDGFRA and PDGFRB in the tumor stroma can reverse the immunosuppressive microenvironment, leading to improved effectiveness of immune checkpoint inhibitors (ICIs)." (PMID 37568781, 2023). "In conclusion, we showed that a combination of expression of PDGFRB, INHBA, MMP11, and galectin-10 in GC tissues may serve as a useful biomarker for survival stratification in patients with pStage II/III gastric cancer following curative resection." (PMID 36139587, 2022).
chordoma (35 papers, 2010 to 2025). Chordomas are rare malignant tumors arising from embryonic remnants of the notochord in axial skeleton. "In the phase II trial with imatinib in PDGFRB/PDGFB-expressing chordomas, the clinical benefit rate (CBR) (CR + PR + SD per RECIST) was 64% after 6 months, with 1 PR and 30 SDs and a median PFS of 9 months." (PMID 40627883, 2025). "For instance, in patients with PDGFRβ‐positive chordomas, the first and second‐line therapies are tyrosine‐kinase (imatinib) and epidermal growth factor receptor (EGFR) inhibitors (erlotinib), respectively." (PMID 36258855, 2022). "Five of the studies (73 patients) focused on PDGFRβ-expressing chordoma, with 45.2% PR, 31.5% SD, and 23.3% PD cases, and eight studies included 12 patients that experienced PD within a short period of time." (PMID 30775316, 2019). "Most patients with PDGFRβ-positive chordoma benefited from imatinib treatment and avoided rapid PD, likely due to tumor necrosis and intra-tumoral subacute bleeding that manifest as liquefaction." (PMID 30775316, 2019). "Fourteen studies (204 patients) analyzed the efficacy of imatinib as monotherapy, of which four studies (181 patients) used RECIST and 3 were focused on PDGFRβ-expressing chordoma." (PMID 30775316, 2019). "By Western immunoblot, PDGFRB was found to be expressed in all chordomas analyzed, although only one case (#10b) also presented activated PDGFRB." (PMID 22613809, 2011). "In contrast, we found activation of PDGFRB only in five out of 12 (42%) chordomas, using the same antibody RTK arrays and using the value of the mean plus the standard deviation within an array as the cut-off." (PMID 22613809, 2011). "Imatinib inhibits cell invasion in malignant peripheral nerve sheath tumors by blocking PDGFRB and it has been found to have antitumor activity in patients with chordoma." (PMID 21171987, 2010). "Imatinib, which has off-target effects acting through the inhibition of platelet-derived growth factor receptor beta (PDGFRβ), is the most thoroughly evaluated therapeutic agent in chordoma, based on the expression of platelet-derived growth factor beta (PDGFβ) or its receptor (PDGFRβ)." (PMID 33308288, 2020). "PDGFRB is also activated in chordomas, but with a lower frequency and/or to a lower level, which might not be detectable by some current standard techniques." (PMID 22613809, 2011). "Interestingly, the frequent activation of PDGFRB in chordomas [21/22 (95%) of cases] was described in the study by Tamborini and collaborators." (PMID 22613809, 2011). "The results of our study compare favorably with previous studies that identified PDGFRB/PDGF, PI3K/AKT, RAS/MAPK, or EGFR as recurrently dysregulated pathways in chordomas." (PMID 40627883, 2025). "While PDGFRB and PARP1 inhibitors have been applied as chordoma therapies, the biological and clinical role of the other candidates is unclear." (PMID 40901948, 2025). "The Hub genes PDGFRB, KDR, and FGF2 are involved in the pathogenesis of chordoma via the Pi3k-Akt signaling pathway and the Rap1 signaling pathway." (PMID 32011476, 2020). "Hub genes PDGFRB, KDR, FGF2 and pi3k-akt signaling pathway, Rap1 signaling pathway will become a new target for the future treatment of chordoma." (PMID 32011476, 2020). "Histopathological features of 42 chordoma specimens, 21 primary and 21 advanced, were assessed by immunohistochemistry and fluorescent in situ hybridization (FISH) using PDGFRB, CSF1R, and EGFR probes." (PMID 22613809, 2011). "In the literature, several RTK, specifically PDGFRA, PDGFRB, KIT, EGFR, MET and HER2, were reported to be expressed in chordoma by immunohistochemistry." (PMID 22613809, 2011). "Advanced chordomas have been reported to overexpress receptor tyrosine kinases (RTKs), including epidermal growth factor receptor (EGFR) and activated platelet-derived growth factor receptor (PDGFRB)." (PMID 41228286, 2025).